RCAN2 (regulator of calcineurin 2)
Description:
Inhibits calcineurin-dependent transcriptional responses by binding to the catalytic domain of calcineurin A. Could play a role during central nervous system development.
Synonyms: MCIP2; DSCR1L1; ZAKI4; ZAKI-4; CSP2
Tractability: PROTAC: its protein half-life has been measured.
Gene: Protein-coding gene on chromosome 6 (46,220,736 to 46,491,972, reverse strand). Ensembl gene ENSG00000172348.
Subcellular location (Human Protein Atlas): Mitochondria; Microtubules; Nucleoplasm; Primary cilium; Vesicles
Gene Ontology:
Molecular function: calcium-dependent protein serine/threonine phosphatase regulator activity; nucleic acid binding
Biological process: calcium-mediated signaling
Cellular component: cytoplasm; nucleus
Genetic constraint (gnomAD): Loss-of-function variants: 9 observed, 23.96 expected, observed/expected ratio (o/e) 0.38, 90% interval 0.22 to 0.65. The upper end of that interval is the gene's LOEUF score, 0.65, which puts it in group 2 of 6, group 1 being the genes least tolerant of losing a copy. Missense variants: 273 observed, 313.51 expected, observed/expected ratio (o/e) 0.87, 90% interval 0.79 to 0.96. Synonymous variants: 109 observed, 121.86 expected, observed/expected ratio (o/e) 0.89, 90% interval 0.76 to 1.05.
Homologues: Orthologues: chimpanzee RCAN2 (99% identical), macaque RCAN2 (99% identical), dog RCAN2 (98% identical), guinea pig RCAN2 (96% identical), pig RCAN2 (95% identical), rat Rcan2 (94% identical), tropical clawed frog rcan2 (82% identical), mouse Rcan2 (71% identical), zebrafish rcan2 (70% identical), rabbit RCAN2 (64% identical), Drosophila melanogaster sra (36% identical), Caenorhabditis elegans rcan-1 (30% identical). Paralogues in human: RCAN3 (58% identical), RCAN1 (52% identical).
Diseases named in the same sentence as RCAN2 in open-access papers:
RCAN2 is named in the same sentence as 23 diseases in open-access papers, as found by Europe PMC text mining. Sharing a sentence is not in itself a finding about the gene and the disease. The quoted sentences say what the papers report.
Obesity (10 papers, 2011 to 2025). Accumulation of substantial excess body fat. "Inactivation of the RCAN2 gene in mice reduced age- and diet-induced obesity by causing a reduction in feed intake." (PMID 38741036, 2024). "The increased serum RCAN2 concentrations were associated with the increased risks of overweight/obesity." (PMID 35733783, 2022). "For obesity risk, in univariate model, model 1 and model 2, every 1-unit increase in serum RCAN2 concentrations was associated with an increased risk of 17.5%, 17.6% and 224.4%, respectively." (PMID 35733783, 2022). "In order to explore the diagnostic value of serum RCAN2 concentrations for obesity, ROC curve analysis was conducted." (PMID 35733783, 2022). "This is the first study to investigate serum RCAN2 concentrations in participants with overweight/obesity and the findings indicated that RCAN2 is a risk factor for overweight/obesity." (PMID 35733783, 2022). "Recently, in C57BL/6J (B6) mice, a golden animal model of human obesity, we found that loss of Rcan2 function ameliorated age- and diet-induced obesity by causing a reduction in food intake." (PMID 28624805, 2017). "Finally, serum RCAN2, especially RCAN2/(AST/ALT) ratio was a candidate biomarker for the diagnostic of overweight/obesity." (PMID 35733783, 2022). "Univariate unconditional logistic regression analysis showed that subjects with the highest tertile of RCAN2 concentrations had 1.539-fold higher risk of obesity than those with the lowest tertile of RCAN2 concentrations (OR = 2.539, 95% CI 1.546-4.170, p < 0.001)." (PMID 35733783, 2022). "Serum RCAN2, especially RCAN2/(AST/ALT) ratio might be the candidate diagnostic markers for obesity." (PMID 35733783, 2022). "Additionally, binary logistic regression analysis showed that serum RCAN2 concentration was associated with overweight/obesity." (PMID 35733783, 2022). "We found that although the loss of Rcan2 function in mice slowed growth in the first few weeks after birth, it also significantly ameliorated age- and diet-induced obesity in the mice by causing a reduction in food intake rather than increased energy expenditure." (PMID 21298050, 2011). "In this present cross-sectional study, we found that serum RCAN2 concentrations were significantly increased in participants with overweight/obesity compared to participants with normal weight." (PMID 35733783, 2022). "This study was the first clinical study to reveal the relationship between serum RCAN2 concentrations and overweight/obesity." (PMID 35733783, 2022). "RCAN2 knockout can resist obesity induced by age and high-energy food, which preliminarily reveals the role of the RCAN2 gene in the regulation process of fat deposition." (PMID 36101325, 2022). "This study aimed to investigate the relationship between serum RCAN2 concentrations and participants with overweight/obesity." (PMID 35733783, 2022). "This study found that serum RCAN2 concentrations were significantly increased in patients with overweight and obesity." (PMID 35733783, 2022). "Participants with the highest serum RCAN2 tertile had a significantly higher prevalence of overweight/obesity than subjects with the lowest serum RCAN2 tertile." (PMID 35733783, 2022). "Unconditional logistic regression analysis of overweight and obesity risks according to the tertiles of serum RCAN2 concentrations and serum RCAN2 concentrations (ng/mL)." (PMID 35733783, 2022). "In the group with obesity, serum RCAN2 concentrations were positively correlated with AST/ALT, UA, TC and TG, and negatively correlated with WBC, NEU, and DBIL (all p < 0.05)." (PMID 35733783, 2022). "Rcan2 increases food intake and plays an important role in the development of age- and diet- induced obesity in male mice." (PMID 28624805, 2017). "Of the candidate genes listed for this chromosome 17 adiposity QTL, Rcan2 is attractive because alterations in this gene reduce diet-induced obesity and liver weight." (PMID 24918027, 2014).
Obesity (continued). "Here, we show that Rcan2 plays an important role in the development of age- and diet-induced obesity." (PMID 21298050, 2011). "Therefore, the function of RCAN2 in adipocytes warrants further investigation, given that VasTg mice were resistant to diet-induced obesity under HFD conditions despite high level expression of the putative orexigenic factor in AT28." (PMID 41372246, 2025). "Therefore, the extrapolation of serum RCAN2 in participants with overweight/obesity diagnosed by BMI criteria should be conducted in other races." (PMID 35733783, 2022). "Recently, RCAN2 was found to be a target gene of peroxisome proliferator-activated receptor gamma (PPARγ), which regulates hepatic lipid deposition in mice with diet-induced obesity." (PMID 35370729, 2022). "Thirdly, this is a cross-sectional study and therefore no causal a conclusion could be drawn between serum RCAN2 concentrations and the increased risk of overweight/obesity." (PMID 35733783, 2022). "More interestingly, alteration in Rcan2 levels was previously found to be correlated with the development of tumor, whereas Rcan2 is also known to regulate the obesity progression via a mechanism-independent of leptin signaling." (PMID 36267816, 2022). "So far, no study has explored the relationship between serum RCAN2 concentrations with overweight and obesity in humans." (PMID 35733783, 2022). "Receiver operation characteristic (ROC) curve analysis revealed that serum RCAN2, especially serum RCAN2/(AST/ALT) ratio, might serve as a candidate biomarker for obesity." (PMID 35733783, 2022). "The relationship between RCAN2-1 and RCAN2-3 and overweight/obesity was not investigated separately, so it is not clear which splicing variant is more important in regulating human weight." (PMID 35733783, 2022).
Sepsis (4 papers, 2022 to 2025). Sepsis is defined as life-threatening organ dysfunction caused by a dysregulated host response to infection. "Collectively, our findings illuminate that miR-377 enhances myocardial hypertrophy caused by sepsis, by targeting Rcan2 and further regulating the Ca2+/CaN signaling pathway." (PMID 36267816, 2022). "On the other hand, the downstream effectors of the RCAN2-Ca2+/CaN signaling pathway in sepsis-induced cardiac hypertrophy remain to be established." (PMID 36267816, 2022). "Additionally, MALAT1 silencing exerts cardioprotective effects on sepsis-induced myocardial injury by reducing inflammation and apoptosis of cardiomyocytes through miR-26a-5p/Rcan2 axis." (PMID 41170388, 2025).
cardiac hypertrophy (3 papers, 2022 to 2025). "RCAN2 variants are also related to BMI and cellular pathways in cardiac hypertrophy and immune response in lymphocytes." (PMID 40883367, 2025). "Furthermore, bioinformatic analyses and mechanistic experimentation in our study revealed that Rcan2 is a downstream gene of miR-377, which was poorly expressed in the cardiac hypertrophy tissues of septic mice." (PMID 36267816, 2022).
gastric cancer (2 papers, 2022). A primary or metastatic malignant neoplasm involving the stomach. "Additionally in gastric cancer, the participation of Rcan2 in tumor progression has been associated with EGFR, nuclear β-catenin, MMP7, laminin-γ2, and VEGF." (PMID 36267816, 2022). "Finally, we verified that TGFB1I1, TGFBR1, SMAD9 and SMAD4 are low expressed in gastric cancer by immunohistochemistry at the protein level, and RCAN2 is also low expressed in gastric cancer." (PMID 36483555, 2022).
infarction (2 papers, 2021 to 2025). A localised pathological necrosis of tissue resulting from obstruction of the blood supply usually by a thrombus, an embolus, or vascular torsion. "In contrast with the circ-RCAN2 downregulation observed in reperfused AMI tissue at 3 days after infarction, constant hypoxia of pCPCs led to significant circ-RCAN2 upregulation, which was dependent on ischemia time, compared to control cells." (PMID 33573240, 2021). "However, they contrast the in vivo findings, where at three days post-closed-chest reperfused porcine infarction, circ-C12orf29 and circ-RCAN2 were downregulated in the infarcted area." (PMID 41226374, 2025).
myocardial infarction (2 papers, 2021 to 2025). Gross necrosis of the myocardium, as a result of interruption of the blood supply to the area, as in coronary thrombosis. "We aimed to (i) confirm the circularity of novel circRNAs (CDR1as, circ-RCAN2, circ-C12orf29) implicated in myocardial infarction, (ii) examine cell-specific regulation patterns under hypoxia, and (iii) assess their effects on cell viability and downstream miRNA targets." (PMID 41226374, 2025). "In this study, we investigated CDR1as, circ-RCAN2 and circ-C12orf29, three circRNAs whose differing expression patterns were described in the context of a large animal model of reperfused myocardial infarction by our group." (PMID 41226374, 2025). "Circ-RCAN2 exhibited differential regulation by myocardial infarction in vivo and by hypoxia in vitro." (PMID 33573240, 2021). "In addition to CDR1as, a 2021 study on porcine myocardium sampled on the third day following a reperfused myocardial infarction, our group uncovered a number of circRNAs with differential expression profiles in infarcted versus healthy myocardium, amongst them circ-RCAN2 and circ-C12orf29." (PMID 41226374, 2025).
adenoma (1 paper, 2016). A neoplasm arising from the epithelium. "Immunohistochemical staining (IHC) analysis of human CRC specimens revealed that RCAN2 was specifically expressed only in cancer cells but not in normal colonic epithelia, adenomas or tumor stroma." (PMID 27526107, 2016).
ciliopathy (1 paper, 2021). A genetic disorder of the cellular cilia or the cilia anchoring structures, the basal bodies, or of ciliary function. "RCAN2 was identified as the gene most highly upregulated by giantin genetic knockout, and was shown by knockdown to suppress ciliopathy phenotypes in giantin mutants." (PMID 34155518, 2021).
Hepatic steatosis (1 paper, 2022). Steatosis is a term used to denote lipid accumulation within hepatocytes. "Systemic knockout of RCAN2 (RCAN2−/−) has been reported to prevent hepatic steatosis in mice fed a high-fat diet." (PMID 35370729, 2022). "The main innovation of the current study is that we first demonstrated that RCAN2 was highly expressed in the liver of mice with fatty liver by qRT-PCR and Western blot, and subsequently confirmed that serum RACN2 levels were also significantly elevated in NAFLD patients." (PMID 35370729, 2022). "This study aimed to evaluate the expression of RCAN2 in the liver of mice with hepatic steatosis and in the serum of NAFLD patients and to explore the relationship between serum RCAN2 levels and NAFLD." (PMID 35370729, 2022). "Elevated RCAN2 mRNA and protein expression was also observed in the liver tissues of HFD-induced fatty liver mice." (PMID 35370729, 2022). "Interestingly, the knockout of RCAN2 in the whole body can significantly reduce the liver weight of high-fat diet-induced obese mice and did not exhibit liver steatosis." (PMID 35370729, 2022).
non-alcoholic fatty liver disease (1 paper, 2022). "However, the association of RCAN2 with non-alcoholic fatty liver disease (NAFLD) in humans remains unclear." (PMID 35370729, 2022).
pancreatic cancer (1 paper, 2021).
steatosis (1 paper, 2022). Increased lipid within the cytoplasm of cells. "However, there are few studies on RCAN2 at present, we have to start with animal or cell research and explore the role and mechanism of RCAN2 in hepatocyte steatosis model through RNAi, overexpression plasmid, adeno-associated virus, and liver specific knockout." (PMID 35370729, 2022).
tuberculosis (1 paper, 2019). A chronic, recurrent infection caused by the bacterium Mycobacterium tuberculosis. "Interestingly, RCAN2 is responsible for the regulation of calcineurin 2 and calcineurin activation promotes the survival of tuberculosis within its host by preventing phagocyte maturation (which is required to destroy tuberculosis;)." (PMID 30763354, 2019).
cancer (5 papers, 2016 to 2021). A tumor composed of atypical neoplastic, often pleomorphic cells that invade other tissues. "Here we report that KRAS mutation may promote cancer cell proliferation by decreasing the expression of RCAN2, and that calcineurin and NFAT signaling may serve as potential therapeutic targets for KRAS-mutated CRC." (PMID 27526107, 2016). "Although further investigation of the correlation between expression in cancer cells and in the interstitium is required, our results suggested that RCAN2 is predominantly expressed at the IF and that KRAS-mutated CRC may promote tumor development due to decreased expression of RCAN2." (PMID 27526107, 2016). "Other genes, such as CALCOCO2, RCAN2, ADI1, ECHS1, PLOD1 and VTI1B were associated with tumorigenesis or angiogenesis in some other cancers 33-35." (PMID 31632497, 2019). "We analyzed the effect of RCAN2 expression on cancer cell proliferation and migration by overexpressing RCAN2 in CRC cell lines." (PMID 27526107, 2016). "RCAN2 is involved in muscle differentiation and cancer progression." (PMID 34440281, 2021). "C1S, FAM20C, KDELR2, and RCAN2 have rarely been reported in cancer." (PMID 33579282, 2021). "Moreover, inhibitory function for cancer cell proliferation dependent on calcineurin was indicated with overexpression and short hairpin RNA knockdown of RCAN2 in human CRC cell lines." (PMID 27526107, 2016). "Moreover, RCAN2 was predominantly expressed at the IF, even in mucosal adenocarcinoma or adenocarcinoma with slight submucosal invasion, where cancer cells and the interstitium share a margin." (PMID 27526107, 2016). "The central gene is PIK3R1 in Module 0, which module contains eight DEGs related to classical cancer pathways (FCER1A, GNG11, IGF1, LIFR, PDK4, PIK3R1, RCAN2, and UGCG)." (PMID 31119098, 2019).
tumor (4 papers, 2016 to 2023). "KRAS mutations in CRC lead to a decrease in RCAN2 expression, resulting in tumor proliferation due to derepression of calcineurin–nuclear factor of activated T cells (NFAT) signaling." (PMID 27526107, 2016). "In conclusion, KRAS mutation in CRC leads to decreased expression of RCAN2, resulting in tumor proliferation by derepression of the calcineurin–NFAT signaling pathway." (PMID 27526107, 2016). "IHC staining revealed that RCAN2 was expressed mainly at the tumor IF in tumor cells and that the expression of this gene was repressed by oncogenic mutation of KRAS in human CRC." (PMID 27526107, 2016). "Moreover, RCAN2 showed higher expression at the invasive front (IF) of tumors (defined as tumor cells or clusters within 500 μm of the IF) than at the tumor centers." (PMID 27526107, 2016). "We identified a novel gene, regulator of calcineurin 2 (RCAN2), that was found to be downregulated in the tumors in Kras-mutated mouse models, which may inhibit calcineurin enzyme activity in CRC and exhibit tumor suppressor function." (PMID 27526107, 2016). "It is preliminarily proved that RCAN2 can regulate TGF-βpathway, thereby affecting tumor immune microenvironment." (PMID 36483555, 2022). "Through GO enrichment analysis and KEGG enrichment analysis, we preliminarily speculated that RCAN2 may regulate the extracellular matrix through TGF-β pathway, thereby affecting the tumor extracellular immune microenvironment." (PMID 36483555, 2022). "Tumor weights were significantly higher in the pSUPER/RCAN2 group than in the pSUPER/non-silencing group (pSUPER/RCAN2; 147 mg vs pSUPER/non-silencing; 31 mg, P=0.013)." (PMID 27526107, 2016). "Tumor growth was observed significantly earlier in the pSUPER/RCAN2 group than in the pSUPER/non-silencing group." (PMID 27526107, 2016). "We used KEGG enrichment analysis to predict that RCAN2 can regulate TGF signal pathway, thereby changing the immune cell infiltration in the tumor microenvironment (including B cells naive, mast cells, T cells regulatory), thereby changing the tumor immune situation." (PMID 36483555, 2022).
RCAN2 also shares sentences with these, for which no sentence is quoted: hypertrophy (2 papers); adenocarcinoma (1); anorexia nervosa (1); Astrocytoma (1); bipolar disorder (1); ischemia (1); ovarian carcinoma (1); schizophrenia (1).